TAAR1 (trace amine associated receptor 1)
Diseases named in the same sentence as TAAR1 in open-access papers (continued):
Sharing a sentence is not in itself a finding about the gene and the disease.
schizophrenia (continued). "Preclinical and clinical data to date suggest that TAAR1 agonists may improve several symptom domains of schizophrenia without causing debilitating motor impairments or metabolic syndrome." (PMID 34947997, 2021). "TAAR1 may be a valuable therapeutic target in areas beyond schizophrenia and psychosis." (PMID 34947997, 2021). "Considering that many of these represent comorbidities of schizophrenia, future studies should assess whether TAAR1 agonists have the potential to treat a spectrum of largely unaddressed schizophrenia symptoms which would otherwise require combination treatments and polypharmacy." (PMID 34947997, 2021). "Furthermore, the beneficial metabolic and antidiabetic effects of TAAR1 agonists raise the question of whether these agents may be uniquely positioned to improve comorbid metabolic disorders in patients with schizophrenia." (PMID 34947997, 2021). "Therefore, the study of TAAR1 contribution to the pharmacological regulation of these processes may help to understand the neurophysiological basis of schizophrenia and develop new treatments to this debilitating disorder." (PMID 31130864, 2019). "In addition, the use of TAAR1 agonists has started to uncover the possible role that TAAR1 may play in the development of diseases like schizophrenia, and Parkinson’s disease." (PMID 29375386, 2017). "In addition, TAAR1 KO exhibited significant deficits in sensorimotor gating measured as impaired prepulse inhibition of acoustic startle, which is a known behavioral signature in schizophrenia regulated by both dopaminergic and glutamatergic mechanisms." (PMID 27092049, 2016). "Ulotaront is a TAAR1 agonist that has advanced to Phase III with Food and Drug Administration (FDA) breakthrough status in schizophrenia." (PMID 41117250, 2025). "Another company, Sunovion Pharmaceuticals (now Sumitomo Pharma), developed a TAAR1/5-HT1AR agonist, SEP-363856 (Ulotaront), which evidenced promising results in a phase II clinical trial for schizophrenia." (PMID 39125796, 2024). "Activation of TAAR1 in dopaminergic, serotonergic, and glutamatergic neurons appears to have an overall inhibitory effect on cell firing, and complementary behavioral observations suggest that agonists could be effective in the treatment of drug addiction, bipolar disorder, and schizophrenia." (PMID 39110804, 2024). "The TAAR1 agonists RO6889450 (Ralmitaront) and SEP-363856 (Ulotaront) are now under active clinical development for schizophrenia treatment." (PMID 39748904, 2024). "The current results, together with prior data, suggest that ulotaront and TAAR1 agonists might regulate the complex interplay between the dopaminergic and glutamatergic systems to improve the reduced signal-to-noise ratio and presynaptic dopamine dysfunction in schizophrenia patients." (PMID 38110609, 2024). "Therefore, TAAR1 may be an efficacious and safe target for schizophrenia treatment." (PMID 37153799, 2023). "One noteworthy candidate is Ulotaront (SEP‐363856), an agent acting as a TAAR1 agonist with 5‐HT1A agonist activity, demonstrating promising outcomes in the treatment of schizophrenia, devoid of extrapyramidal symptoms or metabolic side‐effects." (PMID 38868733, 2023). "SEP-363856 (SEP-856) is a TAAR1 and 5-HT1A receptor agonist, in phase III clinical trials of schizophrenia, which has shown significant efficacy in multiple clinical studies." (PMID 35566106, 2022). "The first developed TAAR1 agonists, RO6889450 (Ralmitaront) and SEP-363856 (Ulotaront), have already been tested in phase II clinical trials for the treatment of schizophrenia, with Ulotaront currently being tested in phase III clinical trials." (PMID 36430544, 2022). "Thus, increasing our knowledge of TAAR1 and its ability to modulate monoaminergic and glutamatergic circuits is not only important for the development of future TAAR1 agonists and their potential therapeutic effects, but possibly also to our understanding of the pathophysiology of schizophrenia." (PMID 34947997, 2021).
schizophrenia (continued). "As such, a mixed 5HT1A/TAAR1 agonist, SEP-363856 (Sunovion Pharmaceuticals), is under phase I clinical trial for schizophrenia, with promising results." (PMID 31643000, 2020). "While the trace amine system’s involvement in psychiatric disorders like schizophrenia and drug addiction has garnered significant attention in research, the role of TAAR1 in stress response and related afflictions has not been as thoroughly explored." (PMID 40351432, 2025). "Recent clinical trials indicate the potential use of TAAR1 agonists for schizophrenia treatment, offering a novel mechanism independent of D2 dopamine receptor blockade." (PMID 39125796, 2024). "Recently, ulotaront, a TAAR1 agonist with 5-HT1A agonist activity, entered Phase 3 clinical trials for the treatment of schizophrenia, raising the prospect of TAAR1 agonism as a clinical intervention for psychiatric disorders involving hyperdopaminergic signaling." (PMID 39518904, 2024). "We co-produced a living systematic review of controlled studies examining TAAR1 agonists in individuals (with or without psychosis/schizophrenia) and relevant animal models." (PMID 39036710, 2024). "For example, TAAR1 agonists modulate presynaptic pathways and regulate dopamine- and glutamatergic neurotransmission in schizophrenia, also reducing negative symptoms and improving cognitive functions in rodent and primate models of this disorder." (PMID 37298431, 2023). "Another TAAR1 agonist, RG7906, is also in phase-II clinical trials for schizophrenia treatment." (PMID 37153799, 2023). "The exploration of newly studied receptors, such as TAAR1 and others, holds the potential to enhance the treatment of negative symptoms and cognitive function in schizophrenia." (PMID 38868733, 2023). "While the selective partial TAAR1 agonist Ralmitaront is currently being tested in Phase 2 clinical trials, Ulotaront (TAAR1 agonist with serotonin 5-HT1A agonist activity) has entered Phase 3 clinical studies to evaluate the treatment of adults and adolescents with schizophrenia." (PMID 36359001, 2022). "The encouraging therapeutic potential of TAAR1 agonists as the first antipsychotic drugs without DRD2 blocking action to treat schizophrenia has been demonstrated in clinical trials." (PMID 35053262, 2022). "Moreover, a new orally active compound, SEP-363856 (Ulotaront, TAAR1 agonist with 5-HT1A receptor activity), has been tested in recent clinical trials as a psychotropic agent for the treatment of psychosis in schizophrenia." (PMID 35887159, 2022). "Whether TAAR1 agonists can reverse impairments in PPI and MMN (e.g., in rodent models of schizophrenia) remains to be investigated." (PMID 34947997, 2021). "Although still no TAAR1 ligand has been approved for clinical use, TAAR1 remains an intriguing and novel drug target for schizophrenia." (PMID 30233365, 2018). "Ulotaront, a trace amine-associated receptor 1 (TAAR1) and serotonin 5-HT1A receptor agonist without antagonist activity at dopamine D2 or the serotonin 5-HT2A receptors, has demonstrated efficacy in the treatment of schizophrenia." (PMID 37550314, 2023). "Notably, TAAR1 agonists not only treat positive symptoms of schizophrenia, but also ease its negative symptoms and cognitive impairments." (PMID 37298431, 2023). "Ulotaront (SEP-363856) is a TAAR1 agonist with 5-HT1A receptor agonist activity, currently being tested in phase III clinical development, with very promising results from the phase II trials, which led to the FDA designation as a breakthrough therapy for the treatment of schizophrenia." (PMID 36976665, 2023). "Thus, TAAR1 has become a promising target for pharmacotherapy, and recent clinical trials suggest a potential use for schizophrenia of TAAR1 agonists with a new mechanism of action not involving blockade of D2 dopamine receptors." (PMID 35328548, 2022).
schizophrenia (continued). "It should also be mentioned that despite the similarly low level of expression of TAAR1, the agonist of this receptor, Ulotaront, showed clinical efficacy in patients with schizophrenia, ameliorating both positive and negative symptoms without causing side effects of currently used antipsychotics." (PMID 36139098, 2022). "Our findings corroborate and extend previous observations on the molecular substrates engaged by this unique, dual TAAR1/5-HT1A receptor agonist and potential antipsychotic that could prove to have major advantages in the treatment of schizophrenia and other psychotic disorders." (PMID 36100653, 2022). "Both preclinical and clinical studies and analyses support the hypothesis that TAAR1 agonists may be effective in treating the negative symptoms of schizophrenia." (PMID 34947997, 2021). "Indeed, Taar1 knockout mice have no overt phenotype, however, exhibiting schizophrenia-like properties." (PMID 31130864, 2019). "Interestingly, TAAR1 agonists are shown to have similar efficacy in improving both positive and negative symptoms of schizophrenia and also were able to improve few cognitive deficits." (PMID 30233365, 2018). "Although the mechanism of action of ulotaront in the treatment of schizophrenia is not fully elucidated, preclinical studies suggest that activation of TAAR1 may normalize hyperdopaminergic activity by decreasing presynaptic dopamine synthesis capacity, release, and/or neuronal firing." (PMID 38110609, 2024). "Thus, it is not surprising that TAAR1 has been shown to affect dopaminergic, serotonergic and glutamatergic signaling and consequently modulate aspects of reward-processing, cognition and mood relevant to schizophrenia and other psychiatric disorders." (PMID 37165101, 2023). "Taken together, these data suggest that TAAR1 agonist is an important negative monoaminergic and positive glutamatergic neurotransmission modulator, which makes it a potential useful target for the pharmacotherapy of neuropsychiatric disorders, including schizophrenia." (PMID 31130864, 2019). "In addition to these developments, the current landscape of novel mechanisms of action includes TAAR-1 agonism, muscarinic receptor agonism, serotonin receptor antagonism/inverse agonism, and glutamatergic modulation, offering targeted treatments for cognitive and negative symptoms of schizophrenia." (PMID 40654581, 2025). "While there is limited publicly available information on ralmitaront’s preclinical profile, ulotaront is designated as a promiscuous TAAR1 and 5-HT1A agonist that is proving able to control the positive, negative, and cognitive symptoms of schizophrenia." (PMID 38004497, 2023).
depression (29 papers, 2016 to 2026). "Background/Objectives: The therapeutic potential of selective trace amine-associated receptor 1 (TAAR1) agonists has been established in multiple animal models of depression and anxiety." (PMID 41462983, 2025). "Trace Amine-Associated Receptor 1 (TAAR1) is a potential target for the treatment of depression and other CNS disorders." (PMID 34445611, 2021). "Intracerebroventricular administration of 3-MT increases behavioral activity, and 3-MT and phenylethylamine have affinity for trace amine-associated receptor 1, which is involved in neuropsychiatric disorders including depression." (PMID 28515684, 2017). "Therefore, agonists targeting TAAR1 have therapeutic potential for treating cognitive deficits and metabolic dysregulation linked with major depressive disorder (MDD) and schizophrenia." (PMID 39812050, 2025). "The association between TA deficiency and affective disorders, such as depression, suggests that TAAR1 activation may serve to stabilize maladaptive mood and emotional fluctuations and contribute to the effects of antidepressants or anxiolytics." (PMID 27092049, 2016). "Collectively, these studies will provide a solid foundation for TAAR1 as a novel therapeutic target for depression." (PMID 40600536, 2026). "In fact, Ulotaront (a TAAR1 agonist) is reported to be currently undergoing phase 2/3 clinical trials in order to test its safety and efficacy in the treatment of major depressive disorder (MDD)." (PMID 40600536, 2026). "Some studies have indicated the potential neural mechanisms related to trace amines and TAAR1 in depression." (PMID 40351432, 2025). "Several TAAR1 agonists have been evaluated in preclinical models of depression, showing potential antidepressant-like properties." (PMID 40351432, 2025). "Several selective TAAR1 agonists have been evaluated in various animal models of depression and anxiety, showing that these compounds can be effective in alleviating depressive and anxiety-like behaviors." (PMID 40351432, 2025). "In fact, the TAAR1 agonist Ulotaront is currently undergoing phase 2/3 clinical trials testing its safety and efficacy in the treatment of major depressive disorder and generalized anxiety disorder." (PMID 38927470, 2024). "A burgeoning literature also establishes the biological plausibility of TAAR1 agonists addressing both mania and depression, in addition to anxiety, psychosis, and features of ADHD." (PMID 39748904, 2024). "Overall, the aim of our research work is to study the effect of the TAAR1 gene knockout on the regulation of energy metabolism and depression-like behavior in mice fed a diet with excess fructose." (PMID 36976665, 2023). "As for electrophysiology, research also showed that TAAR1 activation reversed the impaired excitatory/inhibitory (E/I) balance in the mPFC of depression model animals, which is maintained by glutamatergic excitatory synapses and GABAergic inhibitory synapses." (PMID 37002793, 2023). "Here, ameliorated depression was along with raised TAAR1 and PKA expression of rats after EA treatment." (PMID 37002793, 2023). "In TAAR1‐knockout mice, the selective TAAR1 agonist's effect in the forced swim test (a typical test measuring depression of rodents) was blunted and the extracellular DA in PFC was reduced." (PMID 37002793, 2023). "In the future, activating or inhibiting TAAR1 will be applied to further reveal the mechanism of this receptor in regulating depression." (PMID 37002793, 2023). "TAAR1 agonists can play a certain role in alleviating depression-like and anxiety-like behaviors in animal models." (PMID 36976665, 2023). "Although the E/I ratio wasn't calculated in this experiment, counting on the increased spEPSC and nonsignificant changes of spIPSC, EA tended to present a similar E/I variation trend as TAAR1 in depression treatment." (PMID 37002793, 2023).
depression (continued). "What caught our attention is that preclinical studies have shown that TAAR1 agonists are rational for the treatment of depression and anxiety." (PMID 35566106, 2022). "Alternatively, reduced self-grooming activity is often observed in rodent models of depression and/or neurodegenerative disorders, potentially implicating a complex combination of affective and other pathological states in TAAR1 dysregulation." (PMID 36430544, 2022). "It is suggested that PEA restores dendritic spine number in the hippocampus in the cortisol-induced depression mouse model by the TAAR1 activation and consequent initiation of BDNF/TrkB/CREB signaling." (PMID 35681508, 2022). "There is also evidence for deficits in trace amine activity in depression, and it has been reported that TAAR1 agonists improve affect, displaying antidepressant properties in rodents and nonhuman primates." (PMID 34445611, 2021). "There is evidence that TAAR1 agonists exhibit antidepressant actions in animal depression-like behavioural tests." (PMID 34445611, 2021). "In the 16 years elapsed since its discovery, different classes of synthetic TAAR1 agonists have been developed, and promising results have been obtained in experimental models of drug abuse, stress, depression, narcolepsy, and cognitive impairment." (PMID 29375386, 2017). "Moreover, TAAR1 agonists have attracted interest as potential treatments for depression due to their role in regulating monoamine neurotransmission." (PMID 40600536, 2026). "Thus, this article aims to review evidence of the potential role of TAAR1 in the pathophysiology and treatment of depression." (PMID 40600536, 2026). "With its combined dopamine and norepinephrine reuptake inhibition, as well as TAAR1 agonism, solriamfetol provides a novel mechanism of action for the treatment of depression, possibly offering an effective alternative for patients who do not respond well to traditional antidepressants." (PMID 41057811, 2025). "We hypothesized that EA's effect on depression may be connected with TAAR1's regulation in the monoaminergic system." (PMID 37002793, 2023). "In summary, both SNRIs and TAAR1 agonists could play a certain role in depression." (PMID 35566106, 2022). "Further non-clinical and clinical studies are necessary to validate TAAR1 (and potentially other TAARs) as novel therapeutic targets for the treatment of depression." (PMID 38927470, 2024). "Therefore, to explore the relevant mechanism of EA on depression, we adopted a comprehensive plan of EA and antidepressant therapy to study the effect of this combination on DAT through the mediation of TAAR1." (PMID 37002793, 2023). "Another TAAR1 and TAAR5 ligand T1AM increased ERK levels and adult neurogenesis in the hippocampus, while ERK MAP-kinase is the key molecule of BDNF signaling and mediates antidepressant efficacy in humans and animal models of depression." (PMID 35681508, 2022).